MFN2 (mitofusin 2)
Diseases named in the same sentence as MFN2 in open-access papers (continued):
Sharing a sentence is not in itself a finding about the gene and the disease.
bladder cancer (7 papers, 2013 to 2024). "The underlying mechanisms facilitating the collaboration between circTAF4B and MFN2 in the context of bladder cancer (BCa) are yet to be fully delineated." (PMID 39430741, 2024). "In bladder cancer cell lines, MFN2 overexpression has been shown to inhibit cell proliferation by arresting the cell cycle and inducing apoptosis via caspase-3." (PMID 36289714, 2022). "The Wnt/β-catenin signaling pathway regulates the proliferation and migration of bladder cancer, which can be activated by the ablation of MFN2." (PMID 35413941, 2022). "Studies have shown that the ablation of MFN2 promotes the proliferation and migration of bladder cancer cells by activating the Wnt/β-catenin signaling pathway." (PMID 35413941, 2022). "Recent findings also found a significant correlation between bladder cancer and MFN2 activity; MFN2 was significantly downregulated in bladder cancer patients and its expression was associated with the tumor stage." (PMID 33233365, 2020). "Several studies have investigated the function of Mfn2 in different types of malignancies, including lung, liver and urinary bladder cancers; Mfn2 is thought to promote pro-apoptotic and anti-proliferative functions." (PMID 23797661, 2013). "The downregulation of MFN2 expression has been demonstrated in bladder cancer." (PMID 36289714, 2022).
leukemia (7 papers, 2020 to 2024). A malignant (clonal) hematologic disorder, involving hematopoietic stem cells and characterized by the presence of primitive or atypical myeloid or lymphoid cells in the bone marrow and the blood. "First, we observed that the proportion of GFP+ leukemic cells was significantly increased in mice transplanted with MFN2 OE cells compared to the control, showing that forced mitochondrial fusion increased leukemia burden in vivo." (PMID 36739349, 2023). "Accordingly, mitofusin 2 (MFN2) that medicate mitochondrial fusion and OXPHOS is distinctly upregulated in surviving leukemia cells while the knockout of MFN2 rendered Jurkat sensitivity to DOX." (PMID 36359776, 2022). "One study reported that the expression of Mfn2 is upregulated in cisplatin-resistant murine leukemia L1210/DDP cells compared with the parental L1210 cells." (PMID 35582383, 2021). "We significantly depleted MFN2 or OPA1 in PDX samples, which resulted in shorter mitochondria as measured by confocal imaging, and to a significant reduction of leukemia colony formation (L-CFU)." (PMID 36739349, 2023). "Since MFN2 deletion greatly enhances Jurkat doxorubicin sensitivity, MFN2 and OXPHOS have been discovered to be considerably elevated in surviving leukemia cells." (PMID 35326612, 2022). "In this study, expression of Mitofusin-2 (MFN-2), a GTPase protein mediator of mitochondrial fusion, was found to closely correlate to Jurkat leukemia cell survival post doxorubicin (DxR) assault." (PMID 33204855, 2020). "In accordance with the role of mitochondrial fusion in chemoresistance, MFN2 and oxidative phosphorylation (OXPHOS) have been found to be significantly upregulated in surviving leukemia cells since the knockout of MFN2 substantially increases Jurkat sensitivity to doxorubicin." (PMID 33946271, 2021).
lipodystrophy (7 papers, 2017 to 2025). A congenital or acquired disorder characterized by abnormal loss or redistribution of the adipose tissue in the body. "To interrogate the molecular pathology of MFN2-linked lipodystrophy and facilitate preclinical translational studies we made, and have reported, Mfn2R707W/R707Wmice." (PMID 40759924, 2025). "It is plausible that the specific lipodystrophy-relevant function of MFN2 disturbed by the R707W mutation relates to tethering of mitochondria to other organelles rather than gross OxPhos dysfunction." (PMID 40759924, 2025). "MFN2-related lipodystrophy, in contrast, has only been associated with biallelic mutations, invariably including at least one R707W allele." (PMID 40759924, 2025). "The mitofusin 2 (MFN2) R707W mutation causes debilitating human lipodystrophy featuring lower body adipose loss, upper body adipose hyperplasia, and dyslipidaemic insulin resistance." (PMID 40759924, 2025). "We and others recently identified biallelic R707W mutations in the nuclear MFN2 gene in patients with a remarkable adipose phenotype characterised by extreme upper body adiposity (lipomatosis) and lower body lipodystrophy." (PMID 36722855, 2023). "To obtain an unbiased view of the transcriptional consequences of the lipodystrophy-associated Mfn2 mutation, we next applied bulk RNA sequencing (RNAseq) to BAT and inguinal WAT from HFD-fed mice." (PMID 36722855, 2023). "MFN2-associated lipodystrophy is a mitochondrial disease due to biallelic pathogenic variants including a specific MFN2 p.Arg707Trp substitution." (PMID 35046902, 2021). "The contention that it may be perturbed mitochondrial-ER interactions that underlie MFN2-related lipodystrophy remains to be tested." (PMID 40759924, 2025). "Lipoatrophy, low serum leptin and adiponectin levels, as well as adipose tissue mitochondrial defects, oxidative stress and increased expression of some thermogenic markers, provide evidence of adipose tissue dysfunction in patients with MFN2-associated lipodystrophy." (PMID 35046902, 2021). "However the wide range of different genetic disorders of mitochondrial function now known, which feature a broad range of severity of OxPhos dysfunction, give further credence to the notion that there is more to MFN2 R707W-associated lipodystrophy than simply impaired OxPhos." (PMID 40759924, 2025). "MFN2 R707W, uniquely among the many pathogenic MFN2 variants described to date, causes major morbidity and mortality due to a combination of adipose overgrowth and metabolic complications of lipodystrophy (Rocha 2017, Sawyer 2015, Capel 2018, Carr 2015, Pareyson 2015)." (PMID 40759924, 2025). "This striking anatomical pattern has often led MFN2 R707W-related lipodystrophy to be called “Multiple Symmetrical Lipomatosis (MSL)” although true, encapsulated lipomas are not present." (PMID 40759924, 2025). "We and others have described a severe and unusual form of lipodystrophy – pathological adipose tissue redistribution - caused by biallelic mutation of MFN2, encoding mitofusin 2 (Rocha 2017, Sawyer 2015, Capel 2018, Carr 2015, Pareyson 2015)." (PMID 40759924, 2025). "A fascinating and unexplained feature of MFN2-related lipodystrophy is the striking tissue- and adipose depot-selectivity of the phenotype despite ubiquitous MFN2 expression (Rocha 2017, Sawyer 2015, Capel 2018, Carr 2015, Pareyson 2015)." (PMID 40759924, 2025). "This is a crucial translational question relevant to the safety of potential trials of rapamycin in people with MFN2 R707W-related lipodystrophy." (PMID 40759924, 2025). "A second important motivation was the observation that excess EtOH consumption is strongly associated with the sporadic form of MSL, or Madelung’s disease, that closely resembles MFN2-related lipodystrophy." (PMID 40759924, 2025).
lipodystrophy (continued). "To investigate the molecular pathogenesis of MFN2 R707W-related lipodystrophy, and the role of MFN2 in leptin synthesis and secretion, we generated and characterised homozygous Mfn2R707W/R707W mice." (PMID 36722855, 2023). "The second important question addressed by this study was whether inhibition of mTOR with rapamycin is likely to be safe in MFN2 R707W-related lipodystrophy." (PMID 40759924, 2025). "We next turned from environmental exposures that may worsen the MFN2 R707W lipodystrophy phenotype to assess a candidate treatment, namely the mTORC inhibitor rapamycin (sirolimus)." (PMID 40759924, 2025). "MFN2-related lipodystrophy has some remarkable and currently poorly understood features." (PMID 36722855, 2023). "We also did not study heterozygous animals, but as human MFN2 R707W-associated lipodystrophy shows recessive inheritance, and as even homozygous mice do not exhibit lipodystrophy, a phenotype in heterozygous animals seems unlikely." (PMID 36722855, 2023). "We have previously reported that dermal fibroblasts established from people with MFN2 R707W-related lipodystrophy do not show overt mitochondrial network disruption nor gene expression changes when cultured in standard medium containing 25 mM glucose." (PMID 40759924, 2025). "There was no transcriptional dysregulation of Mfn2 or other lipodystrophy genes in previously published liver or kidney tissue expression studies or in MMA patient-derived kidney cells." (PMID 38271099, 2024). "This may be an indication that impaired oxidative phosphorylation (OxPhos) is not the mechanism mediating MFN2-related lipodystrophy, even though impaired OxPhos is seen in vivo (evidenced by increased serum lactate, and transcriptomic signatures in affected tissue." (PMID 40759924, 2025).
liver disease (7 papers, 2013 to 2025). "Interestingly, Mfn2 was shown to play a protective role in liver disease, as decreased levels of Mfn2 were shown in liver biopsies from patients with non-alcoholic steatohepatitis (NASH) and in mouse models of the condition." (PMID 41367495, 2025). "However, recent studies have focused attention on the role of mitochondrial protein mitofusin 2 (Mfn2) that protects against liver disease." (PMID 32331285, 2020). "Although it has been shown that the expression of Mfn2 was down-regulated in liver diseases, the role of Mfn2 in chronic cholestatic liver diseases has not been investigated." (PMID 23755235, 2013).
lung adenocarcinoma (7 papers, 2019 to 2024). A carcinoma that arises from the lung and is characterized by the presence of malignant glandular epithelial cells. "According to certain authors, the phenotype observed in various lung adenocarcinoma cell lines was associated with decreased expression of the mitochondrial fusion mediator MFN-2 and elevated expression of the mitochondrial fission regulator DRP-1." (PMID 39199596, 2024). "In lung adenocarcinoma, some studies have implicated MFN2 in exerting tumor‐promoting effects, whereas tumor‐suppressing effects of MFN2 have also been reported." (PMID 36877954, 2023). "On the contrary, our previous study found that Mfn2 expression in cisplatin-resistant lung adenocarcinoma A549/DDP cells was lower than cisplatin-susceptible A549 cells." (PMID 35582383, 2021). "Second, we demonstrated that Mfn2 expression in cisplatin-resistant lung adenocarcinoma A549/DDP cells was lower than that in cisplatin-susceptible A549 cells." (PMID 35582383, 2021). "Furthermore, we assessed the association of Mfn2 expression with lung adenocarcinoma clinical features." (PMID 35582383, 2021). "Here, we found that MFN2 deficiency resulted in decreased UCP4 expression and mitochondrial dysfunction in lung adenocarcinoma." (PMID 36877954, 2023). "In lung adenocarcinoma patient samples also MFN2 is overexpressed, and its downregulation in a lung adenocarcinoma cell line decreases proliferation and invasion." (PMID 37019897, 2023). "Shenqi Fuzheng injection effectively improved cisplatin sensitivity in human lung adenocarcinoma A549/DDP cells through Mfn2-mediated cell cycle arrest and apoptosis." (PMID 35582383, 2021). "The protein expression of Mfn2 in a lung adenocarcinoma tissue chip was detected by immunohistochemistry staining." (PMID 35582383, 2021). "Next, we examined Mfn2 protein expression in 75 pairs of human lung adenocarcinoma tissue microarrays via IHC staining, and the results show that Mfn2 expression level in lung adenocarcinoma was lower than in the matched paracancerous tissues (P < 0.001)." (PMID 35582383, 2021). "In conclusion, we first confirmed that the expression of Mfn2 in lung adenocarcinoma was lower than that in matched paracancerous tissues." (PMID 35582383, 2021). "The results show that the expression level of Mfn2 in lung adenocarcinoma was lower than that in matched paracancerous tissues." (PMID 35582383, 2021). "It is worth noting that the higher expression of Mfn2 has also been reported in lung adenocarcinoma tissues as compared to adjacent normal tissues, and Mfn2 knockdown results in impaired cancer cell proliferation." (PMID 31551926, 2019). "Here, we investigated the effect of MFN2 regulation on mitochondria in lung adenocarcinoma." (PMID 36877954, 2023). "The role of MFN2 in lung adenocarcinoma remains highly debated." (PMID 36877954, 2023). "Finally, we demonstrated that low expression levels of MFN2 and UCP4 in lung adenocarcinoma are associated with poor clinical prognosis." (PMID 36877954, 2023). "Second, the expression of MFN2 was found to be highest in the A549 lung adenocarcinoma cell line." (PMID 36877954, 2023). "Until now, few studies have focused on the role of Mfn2 in lung adenocarcinoma, some of which presented results inconsistent with our study showing that Mfn2 was downregulated in human lung adenocarcinoma tissues and Mfn2 exhibited antitumor activity in vivo and in vitro." (PMID 35582383, 2021). "Finally, we found that co-treatment with SMI and cisplatin enhanced lung adenocarcinoma apoptosis through regulation of Mfn2-dependent mitochondrial dynamics." (PMID 35582383, 2021). "To determine whether Mfn2 is related to chemical resistance in NSCLC, we compared the expression level of Mfn2 in cisplatin-sensitive lung adenocarcinoma A549 cells and cisplatin-resistant A549/DDP cells." (PMID 35582383, 2021).
lung adenocarcinoma (continued). "In our study, we found that a low expression of Mfn2 was related to cisplatin resistance in lung adenocarcinoma cells, and the expression of Mfn2 in A549/DDP cells was significantly increased following co-treatment with cisplatin and SMI, followed by reduced mitochondrial fragmentation." (PMID 35582383, 2021). "However, the role of MFN2 in lung adenocarcinoma remains controversial." (PMID 36877954, 2023). "Moreover, low levels of MFN2/UCP4 correlate with poor prognosis in lung adenocarcinoma." (PMID 36877954, 2023). "To further clarify the role of Mfn2 in NSCLC, we compared the Mfn2 expression levels in 75 pairs of lung adenocarcinoma and matched paracancerous tissues." (PMID 35582383, 2021). "Lung adenocarcinoma tissues also express high levels of DRP1 and lower levels of MFN-2 (mitofusin 2) when compared to adjacent normal lung." (PMID 32397535, 2020).
metabolic syndrome (7 papers, 2013 to 2025). A cluster of metabolic risk factors for CARDIOVASCULAR DISEASES and TYPE 2 DIABETES MELLITUS. "Moreover, dapagliflozin induced improvement of fusion-fission proteins (Mfn-1, Mfn-2, and Fis-1) in a rat model of metabolic syndrome." (PMID 38892417, 2024). "Similarly, dapagliflozin normalizes the Mfn1/Mfn2 ratio in the rat model of metabolic syndrome, thereby suppressing prolonged ventricular repolarization." (PMID 31970162, 2019). "However, this acute exercise performed by metabolic syndrome patients reduces the gene expression of CoxIV and Tfam and maintains the basal expression of MitoND5, UCP3, HO1, MnSOD, GPx, CAT, Mfn1, Mfn2, Nrf2 and PGC1α." (PMID 34198661, 2021).
steatosis (7 papers, 2014 to 2025). Increased lipid within the cytoplasm of cells. "Mfn1, Mfn2, and Opa1 mRNA expression in steatosis LO2 cells was also significantly lower, while the mRNA expression levels of Fis1 and Drp1 were much higher than those in the control (p < 0.01) and the taurine groups (p < 0.01)." (PMID 37373507, 2023). "The histological characteristics of inflammation and steatosis are also attenuated by salvianolic acid B by enhancing Mfn2-related mitochondrial fusion and reducing mitochondria-related hepatocyte death." (PMID 32213662, 2020). "Furthermore, hepatic Mfn2 levels are lower both in mouse models and in patients with steatosis/steatohepatitis." (PMID 36984762, 2023). "Moreover, omega 3 fatty acids reverted mitochondrial fission during in vitro hepatocyte steatosis through Mfn2 upregulation and tubular elongation." (PMID 34575980, 2021). "Moreover, reduced Mfn2 levels are also detected in mouse models of steatosis or NASH, and its re-expression in a NASH mouse model ameliorates the disease progression." (PMID 32213662, 2020). "Moreover, a previous study reported mitochondrial fission during in vitro hepatocyte steatosis and its reversal by omega-3 fatty acids (i.e., tubular elongation and Mfn2 upregulation)." (PMID 24663492, 2014). "In macrophages, the STING–YAP axis regulates steatosis by reprogramming lipid metabolism through a pathway involving transmembrane protein 205 (TMEM205), mitofusin 2 (MFN2), and protein disulfide isomerase (PDI)." (PMID 40392981, 2025).
endothelial dysfunction (6 papers, 2014 to 2025). In vascular diseases, endothelial dysfunction is a systemic pathological state of the endothelium (the inner lining of blood vessels) and can be broadly defined as an imbalance between vasodilating and vasoconstricting substances produced by (or acting on) the endothelium. "In our study, we also found that levels of Mfn-2 increased in preeclampsia patients parallel to increased anti-angiogenic factors such as sFlt-1 and sEng, indicating increased endothelial dysfunction due to hypoxia." (PMID 39166673, 2024). "In this study, we detected more elevated serum maternal Mfn-2 levels in response to increased hypoxia and endothelial dysfunction in sPE." (PMID 39166673, 2024). "Endothelial dysfunction was observed in PA-treated HAECs, including impaired total antioxidant capacity, cell viability, NO levels, and eNOS, MFN2 and UQCRC1 protein levels, as well as significant up-regulation of IL6, MMP1, and CHOP mRNA levels." (PMID 37237885, 2023). "In this study, we evaluated the role of MFN2 absence in PA-induced endothelial dysfunction." (PMID 37237885, 2023). "In addition, H2-CME prevented PA-induced endothelial dysfunction by restoring mitofusin-2 (MFN2) levels and maintaining redox balance." (PMID 37237885, 2023). "To determine whether mitochondrial fission is involved in endothelial dysfunction in vivo, we explored the expression of Drp1 and Mfn2 in endothelium via real-time PCR." (PMID 35906216, 2022). "We hypothesize that in HHcy there is increased mitochondrial fission due to altered Mfn‐2/Drp‐1 ratio, which leads to endothelial dysfunction and collagen deposition in the mesenteric artery inducing vascular remodeling." (PMID 24771691, 2014). "In addition, the inhibition of ANRIL also reversed the increase in Drp1 expression and up-regulate Mfn2 expression, suggesting that ANRIL could mediate endothelial dysfunction caused by IS stimulation." (PMID 35906216, 2022). "In addition, co-treatment with PA and NAC reduced endothelial dysfunction, including restoration of total antioxidant capacity, cell viability, NO levels, and eNOS, DRP1, MFN2, NDUFS3, and UQCRC1 protein levels, as well as inhibition of IL6 and CHOP mRNA levels." (PMID 37237885, 2023).